CLDN6 (claudin 6)
Description:
Plays a major role in tight junction-specific obliteration of the intercellular space. (Microbial infection) Acts as a receptor for hepatitis C virus (HCV) entry into hepatic cells.
Tractability: Antibody: UniProt places it where antibodies can reach, with high confidence; its Gene Ontology location is reachable by antibodies, with high confidence; UniProt predicts a signal peptide or a membrane-spanning region. PROTAC: ubiquitination databases record sites on it.
Gene: Protein-coding gene on chromosome 16 (3,014,705 to 3,020,071, reverse strand). Ensembl gene ENSG00000184697.
Subcellular location: Cell junction, tight junction; Cell membrane
Pathways (Reactome):
Cell-Cell communication: Tight junction interactions
Gene Ontology:
Molecular function: protein binding; virus receptor activity; cell-cell adhesion mediator activity; identical protein binding; structural molecule activity
Biological process: bicellular tight junction assembly; calcium-independent cell-cell adhesion; cell adhesion; symbiont entry into host cell
Cellular component: plasma membrane; bicellular tight junction; apicolateral plasma membrane; membrane
Genetic constraint (gnomAD): Loss-of-function variants: 1 observed, 1.9 expected, observed/expected ratio (o/e) 0.53, 90% interval 0.17 to 1.76. That is too few expected variants to judge how well the gene tolerates losing a copy. Missense variants: 279 observed, 282.96 expected, observed/expected ratio (o/e) 0.99, 90% interval 0.89 to 1.09. Synonymous variants: 144 observed, 132.13 expected, observed/expected ratio (o/e) 1.09, 90% interval 0.95 to 1.25.
Homologues: Orthologues: macaque CLDN6 (99% identical), rabbit CLDN6 (92% identical), pig CLDN6 (91% identical), chimpanzee CLDN6 (90% identical), dog CLDN6 (89% identical), guinea pig CLDN6 (89% identical), mouse Cldn6 (88% identical), rat Cldn6 (86% identical). Paralogues in human: CLDN9 (70% identical), CLDN4 (60% identical), CLDN3 (58% identical), CLDN5 (53% identical), CLDN8 (45% identical), CLDN17 (45% identical), CLDN1 (42% identical), CLDN7 (42% identical), CLDN14 (40% identical), CLDN19 (40% identical), CLDN2 (39% identical), CLDN22 (35% identical), and 10 more.
Diseases named in the same sentence as CLDN6 in open-access papers:
CLDN6 is named in the same sentence as 103 diseases in open-access papers, as found by Europe PMC text mining. Sharing a sentence is not in itself a finding about the gene and the disease. The quoted sentences say what the papers report.
breast carcinoma (55 papers, 2012 to 2025). "Meanwhile, we found that CLDN6 was associated with multiple NRF2 target genes in the TCGA breast cancer cohort." (PMID 39984471, 2025). "Given our finding that CLDN6 is associated with ferroptosis in breast cancer patients, CLDN6 triggering ferroptosis in breast cancer cells was subsequently observed in terms of cell viability, ultrastructure, and biochemical processes." (PMID 39984471, 2025). "Treatment of MDA-MB-231 and ERβ-overexpressing SK-BR-3 breast cancer cells with the Erβ-specific agonist DPN caused autophagy through CLDN6-mediated upregulation of the key mediator of autophagy beclin-1." (PMID 39175529, 2024). "Overexpression of CLDN6 inhibits the metastasis of breast cancer, but the underlying mechanism is incompletely understood." (PMID 36935496, 2023). "We have found that CLDN6 suppressed breast cancer cells proliferation, but the underlying mechanism is not well understood." (PMID 35008557, 2021). "Methylation of CLDN6 is associated with a decrease in mRNA expression in esophageal squamous cell carcinoma and breast cancer." (PMID 34948213, 2021). "We subsequently constructed the Kaplan–Meier curve of breast cancer patients using the GEO database (n = 2032, best cut–off), which showed that a lower CLDN6 level was associated with a worse relapse–free survival (RFS)." (PMID 35008557, 2021). "We previously observed CLDN6 loss in breast cancer tissues, and functional experiments showed that CLDN6 inhibits EMT in cells." (PMID 32093760, 2020). "Given that CLDN6 is strongly associated with autophagy in breast cancer cells, we wanted to explore the role of CLDN6 in autophagy." (PMID 31412908, 2019). "In MCF-7 and SKBR-3 breast cancer cells, DNA hypermethylation is associated with low expression of claudin-6." (PMID 31717460, 2019). "In the current study, we explored the role of CLDN6 in breast cancer chemoresistance and the underlying mechanism, and found that high level expression of CLDN6 conferred chemoresistance on MCF-7 and MCF-7/MDR cells to ADM, 5-FU, and DDP through GSTP1." (PMID 29116019, 2017). "Our previous study showed that CLDN6 silencing in breast cancer cells was associated with DNMT1 mediated DNA methylation." (PMID 28867761, 2017). "Clinicopathologic analysis revealed that GSTP1 expression was positively associated with CLDN6 in human breast cancer samples." (PMID 29116019, 2017). "Our investigation showed that CLDN6 expression was associated with DNA methylation in breast cancer tissues and cells." (PMID 27461117, 2016). "It is reported that apoptosis signal-regulating kinase 1 is associated with the effect of claudin-6 in breast cancer." (PMID 23919729, 2013). "Loss of CLDN6 may lead to increased HIF-1α-driven breast cancer metastasis in a SUMOylation-dependent manner." (PMID 40508219, 2025). "Our study showed that CLDN6 was associated with ferroptosis in breast cancer patients." (PMID 39984471, 2025). "Deregulation of CLDN6 expression and distribution has been associated with epithelial cancer progression in non-small-cell lung, ovarian, cervical, and breast carcinomas, but in the latter, its function as a tumor-promoting or tumor suppressor gene has been recognized." (PMID 37762277, 2023). "Notably, Quan C found that CLDN6 was preferentially expressed in mammary epithelial cells of Copenhagen rats, which were extremely resistant to mammary cancer development, compared with susceptible Buffalo." (PMID 34948213, 2021). "Our findings are significant for the aetiology of CLDN6 loss in breast cancers." (PMID 32093760, 2020). "Our data provide a molecular mechanistic insight indicating that CLDN6 loss may lead to elevated HIF-1α-driven breast cancer metastasis in a SUMOylation-dependent manner." (PMID 32093760, 2020). "CLDN6 plays an important role in the migration, invasion and metastasis of breast cancer cells, but the exact underlying mechanism remains unclear." (PMID 32093760, 2020).
breast carcinoma (continued). "Our data support the hypothesis that breast cancer patients with primary CLDN6 loss are more likely to have tumour metastasis due to lack of feedback mechanism to inhibit HIF-1α stability." (PMID 32093760, 2020). "Next, we asked whether the inhibitory effect of ERβ on migration and invasion of breast cancer cells was associated with CLDN6." (PMID 31412908, 2019). "In addition, 69.9 % of 23 breast cancer tissues showed DNA methylation with low expression of CLDN6, indicating that CLDN6 expression was negatively associated with DNA methylation." (PMID 27461117, 2016). "Taken together, these findings suggest that CLDN6 promotes chemoresistance in breast cancer cells through the induction of protective autophagy both in vitro and in vivo." (PMID 40959289, 2025). "Here we proposed for the first time that ferroptosis was an integral link for CLDN6 to exert the anticancer effect in breast cancer." (PMID 39984471, 2025). "In this study, we focused on the role and mechanism of CLDN6 in inducing protective autophagy and promoting chemoresistance in breast cancer." (PMID 40959289, 2025). "This study aims to validate the potential of CLDN6 as a biomarker for protective autophagy, providing a novel therapeutic approach for chemoresistant breast cancer patients." (PMID 40959289, 2025). "Based on ROC plotter and TMA, we identified that CLDN6 is a potential biomarker for the chemoresistance of breast cancer patients." (PMID 40959289, 2025). "The C&F classifier demonstrated strong predictive power in TCGA and the TMA of breast cancer, outperforming the CLDN6 expression and ferroptosis in robustness." (PMID 39984471, 2025). "We found that CLDN6 was highly expressed in normal luminal epithelial but was underexpressed in breast cancer cell, and showed tissue specificity in various tumors and normal." (PMID 39984471, 2025). "Here we found that CLDN6 promotes the NRF2 nuclear export to induce ferroptosis by the AKT/GSK3β/FYN axis in breast cancer cells." (PMID 39984471, 2025). "It appears that CLDN6 has a “pro-oncogenic” effect under chemotherapy conditions, contradicting its cancer-suppressive role in breast cancer." (PMID 40959289, 2025). "CLDN6 promotes or inhibits breast cancer depending on its subcellular localization and different stress conditions." (PMID 40959289, 2025). "Growing evidence suggests that CLDN6 functions as a tumor suppressor in breast cancer through multiple mechanisms." (PMID 40687428, 2025). "Our study presents a novel biomarker for chemotherapy-induced protective autophagy and establishes a theoretical and experimental foundation for targeting CLDN6 to enhance chemosensitivity in breast cancer patients." (PMID 40959289, 2025). "In the present study, we first assessed the relationship between CLDN6 expression and patient survival after chemotherapy in breast cancer patient tissues." (PMID 40959289, 2025). "Our latest study revealed that CLDN6 is mainly located in the cell membrane and inhibits the growth and metastasis of breast cancer." (PMID 40959289, 2025). "In summary, we found that CLDN6 promotes chemoresistance through the activation of protective autophagy in breast cancer." (PMID 40959289, 2025). "Our previous research revealed that CLDN6 is expressed at low levels in breast cancer, while its overexpression inhibits breast cancer growth and metastasis." (PMID 40959289, 2025). "This suggests that under chemotherapy conditions, cytoplasmic CLDN6 induces breast cancer chemoresistance through protective autophagy." (PMID 40959289, 2025). "We previously identified CLDN6 as a pivotal tumor suppressor in breast cancer and unexpectedly discovered that overexpression of CLDN6 resulted in characteristic ultrastructural alterations of ferroptosis." (PMID 39984471, 2025). "Next, AMPK was silenced in breast cancer cells overexpressing CLDN6, and the WB results showed a notable decrease in the expression of p-ULK1." (PMID 40959289, 2025).
breast carcinoma (continued). "Our findings demonstrated that CLDN6 induced protective autophagy, which contributed to the resistance of breast cancer cells to chemotherapy in vitro and in vivo." (PMID 40959289, 2025). "We previously made the unexpected discovery that ultrastructural changes of ferroptosis occurred in breast cancer cells overexpressing CLDN6." (PMID 39984471, 2025). "Our previous data showed that CLDN6, as a suppressor gene, is underexpressed in breast cancer and here our validation of CLDN6 expression extends to RNA array and single-cell sequencing datasets." (PMID 39984471, 2025). "To clarify the role of PBM in CLDN6 linking DLG1 to PBK, we transfected PBM-deficient CLDN6 in breast cancer cells." (PMID 39984471, 2025). "Downregulation of claudin proteins has been reported in many cancer types, including claudin-2 and claudin-6 in breast cancer and claudin-18 in gastric cancer." (PMID 38540693, 2024). "Another great example of how CLDNs’ effects are variable in different cancers is how CLDN6 promotes the EMT in gastric cancer while its downregulation in breast cancer promotes cancer invasiveness and progression." (PMID 38731853, 2024). "Claudin-6 (CLDN6), a tight junction protein and tumor suppressor, was found to be a direct target of ERβ in breast cancer cells." (PMID 39175529, 2024). "Estrogen receptor β inhibits breast cancer cells migration and invasion through CLDN6-mediated autophagy." (PMID 37780567, 2023). "Together, our results suggested that overexpressed CLDN6 induced autophagy and enhanced autophagic flux in breast cancer cells." (PMID 36935496, 2023). "Our study enriches the theoretical basis for CLDN6 as a potential biomarker for breast cancer diagnosis and therapy." (PMID 36935496, 2023). "In CLDN6-overexpressing breast cancer cells, CLDN6 interacted with JNK, but CLDN6ΔPBM lost this function." (PMID 36935496, 2023). "The results showed that WIP knockdown inhibited F-actin aggregated around the nucleus in CLDN6-overexpressing breast cancer cells, which suggested that CLDN6 regulated actin cytoskeleton through WIP." (PMID 36935496, 2023). "ChIP assay showed that c-Jun bound to the predicted site of WIP gene promoter in CLDN6-overexpressing breast cancer cells." (PMID 36935496, 2023). "The data provide a new insight into the inhibitory effects of CLDN6-mediated autophagy on breast cancer metastasis, and revealed the new mechanism of CLDN6 regulating autophagy through WIP-dependent actin cytoskeleton." (PMID 36935496, 2023). "CLDN6 expression in breast cancer is regulated by transcription factors such as HIF-1a, FoxA2, Gata6, and TTF-1 at the claudin 6 promoter." (PMID 37762277, 2023). "Using mRNA microarray, we previously observed that differential genes enriched in the regulation of actin cytoskeleton in CLDN6-overexpressing breast cancer cells." (PMID 36935496, 2023). "Since the importance of autophagy in tumor metastasis, we examined the effect of CLDN6 in regulating autophagy in breast cancer cells." (PMID 36935496, 2023). "In present study, we reported that CLDN6 regulated breast cancer metastasis via autophagy in vitro and vivo." (PMID 36935496, 2023). "CLDN6 was also found to play a role in cancer cell migration and invasion in breast cancer, hepatocellular carcinoma, and gastric cancer." (PMID 37655157, 2023). "Consistently, we found that treatment with autophagy inhibitor reversed the inhibitory effect of CLDN6 overexpression on breast cancer metastasis both in vivo and vitro, which suggested that CLDN6 suppressed breast cancer metastasis via autophagy." (PMID 36935496, 2023). "CLDN6 inhibits breast-cancer metastasis and cell invasion and has low expression levels in breast cancer." (PMID 37345019, 2023).
breast carcinoma (continued). "Our findings enrich the theoretical basis for CLDN6 as a potential biomarker for breast cancer diagnosis and therapy." (PMID 36935496, 2023). "Using mRNA sequencing we found WIP expression was upregulated in CLDN6-overexpressing breast cancer cells." (PMID 36935496, 2023). "In this study, we focused on the effect and mechanism of CLDN6 in inhibiting breast cancer metastasis." (PMID 36935496, 2023). "On the other hand, SMAD2 suppresses CLDN6 expression through DNMT1-mediated methylation of CLDN6 promoter, thus promoting cell migration and invasion in breast cancer." (PMID 36672179, 2023). "In summary, our results showed that CLDN6 inhibited breast cancer metastasis by upregulating WIP expression in vitro and vivo." (PMID 36935496, 2023). "To validate this, we treated CLDN6-overexpressing breast cancer cells with the JNK inhibitor SP600125." (PMID 36935496, 2023). "We treated CLDN6-overexpressing breast cancer cells with Jasplakinolide to prevent F-actin depolymerization, and found that Jasplakinolide treatment promoted autophagy." (PMID 36935496, 2023). "Previously, we have proved that CLDN6 expression is decreased in human breast cancer compared with that in normal breast tissues." (PMID 36935496, 2023). "Furthermor, we treated CLDN6-overexpressing breast cancer cells with CK666, a cell-permeable drug that inhibits Arp2/3 activity, to inhibit actin cytoskeleton formation." (PMID 36935496, 2023). "Our group revealed that ERβ inhibited breast cancer cells migration and invasion through CLDN6-mediated autophagy." (PMID 36935496, 2023). "To further validate the role of CLDN6-induced autophagy in breast cancer metastasis in vivo, we established lung metastasis mouse models with BALB/c-nu mice." (PMID 36935496, 2023). "Previously, we have cloned CLDN6 as a candidate suppressor gene of breast cancer from COP rat mammary epithelial cells for the first time." (PMID 36935496, 2023). "Our study found that CLDN6 overexpression led to actin cytoskeleton rearrangement in breast cancer cells." (PMID 36935496, 2023). "WIP knockdown resulted in actin cytoskeleton rearrangement and inhibited autophagy in CLDN6-overexpressing breast cancer cells." (PMID 36935496, 2023). "Our findings illustrate the role of CLDN6-mediated autophagy in breast cancer metastasis, which makes CLDN6 possible as a biomarker to monitor autophagy status of breast cancer in vivo." (PMID 36935496, 2023). "CLDN6 expression is linked to apoptosis signal-regulating kinase 1 (ASK1) expression, and restoring CLDN6 expression in breast cancer cells reduces ASK1 phosphorylation, activates the downstream target proteins JNK and p38 kinase, and induces apoptosis." (PMID 36620607, 2022). "Compared with adjacent normal tissues, CLDN6 expression levels are significantly reduced in breast cancer tissues." (PMID 36620607, 2022). "New data prove that ERβ inhibits breast cancer cell migration and invasion via Claudin-6 (CLDN6)-mediated autophagy." (PMID 35565393, 2022). "GSTP1 was found to be upregulated in CLDN6-overexpressing and multidrug-resistant estrogen-receptor positive (ER+) breast cancer cells." (PMID 33946704, 2021). "In summary, we found that CLDN6 was low-expressed in breast cancer, and CLDN6 overexpression inhibited cell proliferation in vitro and in vivo." (PMID 35008557, 2021). "In conclusion, our results supported that CLDN6 acted as a potential prognostic biomarker of breast cancer and provided new insights into the mechanism by which CLDN6 inhibited breast cancer proliferation." (PMID 35008557, 2021). "Collectively, these data indicated that CLDN6 was reduced in breast cancer, and breast cancer patients with lower CLDN6 expression had a worse prognosis." (PMID 35008557, 2021). "In vitro and in vivo experiments showed that CLDN6 overexpression inhibited breast cancer proliferation." (PMID 35008557, 2021). "Overexpression of CLDN6 can inhibit the proliferation, migration and invasion of breast cancer cells." (PMID 34405008, 2021).